HMOX1 (heme oxygenase 1)
Diseases named in the same sentence as HMOX1 in open-access papers (continued):
Sharing a sentence is not in itself a finding about the gene and the disease.
prostate carcinoma (continued). "HMOX1 inhibitor suppresses thyroid tumor growth and potentiates metformin efficacy in prostate cancer cells." (PMID 35370706, 2022). "This study demonstrates inhibition of antibiotic‐resistant mycoplasma M. hyorhinis replication in human prostate cancer cells by the inducible cytoprotective enzyme heme oxygenase‐1 (HO‐1)." (PMID 34375508, 2021). "We describe here the striking > 90% inhibitory effect of hemin, a natural inducer of the cytoprotective enzyme heme oxygenase‐1 (HO‐1), on M. hyorhinis replication in chronically infected LNCaP prostate cancer cells." (PMID 34375508, 2021). "HMOX1 has a protective effect on androgen-dependent prostate cancer cells during androgen deprivation therapy, promoting the transformation into androgen-independent prostate cancer cells and overexpression." (PMID 34722497, 2021). "In a recent study, we assessed how hemin, a pharmacologic inducer of heme oxygenase-1 (HO-1), has an impact on prostate cancer development in vivo." (PMID 32408492, 2020). "MYC, ATF3, PMEPA1, AURKB, and HMOX-1 were identified as novel targets of curcumin in both less aggressive and highly aggressive metastatic prostate cancer cells in our study." (PMID 31581661, 2019). "In contrast, HMOX-1 inhibits the migration and growth of prostate cancer cells by modulating the architecture of cell-cell interactions." (PMID 31581661, 2019). "Recently, RNA-seq data from prostate cancer cells overexpressing HMOX1 showed that HMOX1 down-modulated the PLAU pathway related to cell adhesion and cell-cell communication." (PMID 31527696, 2019). "Our data confirmed the tumor-inhibitory effects of HMOX-1 gene in prostate cancer cells, which was up-regulated by curcumin treatment." (PMID 31581661, 2019). "We find that five of these genes (IRF2BP2, EDARADD, GPI, HMOX1, KIF3C) were over-expressed in patient samples, and the overexpression was significantly associated with prostate cancer relapse (the onset of metastatic disease) as individual and as a group." (PMID 30478344, 2018). "Surprisingly, in some breast, lung and prostate cancer cells high HMOX1 expression correlates with decreased growth." (PMID 29560114, 2018). "Overexpression of HMOX1 in prostate cancer cells downregulated the MMP9 expression and decreased the invasive potential." (PMID 22461839, 2012). "Interestingly, after castration, LNCaP failed to form tumors, whereas treatment with PC3-derived exosomes resulted in tumor formation in prostate cancer along with increased expression of HMOX1." (PMID 39327610, 2024). "During this process, androgen-independent prostate cancer cells exhibit higher levels of HMOX1." (PMID 39850572, 2024). "Furthermore, HMOX1 emerges as a potential target or biomarker for monitoring and potentially slowing the transition of prostate cancer to CRPC." (PMID 39850572, 2024). "Therefore, further understanding the role of the antioxidant HMOX1 in prostate cancer or other cancers is crucial." (PMID 39850572, 2024). "Moreover, it has been shown that exosomes produced by androgen-independent prostate cancer cells upregulate HMOX1, promoting the transition of androgen-dependent prostate cancer cells to androgen independence." (PMID 39850572, 2024). "In this study, we investigated whether expression of the metabolic gene, heme oxygenase-1 (HO-1) in tumor microenvironment imparts significant effects on prostate cancer progression." (PMID 26418896, 2015). "Additionally, NAC treatment attenuated S.C-induced HMOX1 expression in prostate cancer cells." (PMID 38195593, 2024). "In prostate cancer cells, TMAO treatment alone increased HMOX1 expression; SB203580 alone reduced HMOX1 expression." (PMID 39850572, 2024). "CXCL5 evinces antioxidant properties by upregulating heme oxygenase-1 (HO-1) to counteract H2O2-induced reactive oxygen species (ROS) in a CXCR2-dependent manner in WPMY-1 and prostate cancer cells." (PMID 39765818, 2024).
prostate carcinoma (continued). "It is worth noting that key bone markers were significantly upregulated in prostate cancer cells cocultured with primary mouse osteoblasts induced by HO-1, which proved that HMOX1 plays an important role in bone metastasis of prostate cancer." (PMID 34722497, 2021). "CUR can also induce the demethylation of the nuclear factor erythroid-2 (NF-E2) related factor-2 (NRT2) gene which in turn activates (NQO1), heme oxygenase-1 (HO1) and an antioxidant stress pathway which can prevent growth in mouse TRAMP-C1 prostate cancer cells." (PMID 28611316, 2017).
Alzheimer disease (98 papers, 2008 to 2026). A progressive, neurodegenerative disease characterized by loss of function and death of nerve cells in several areas of the brain leading to loss of cognitive function such as memory and language. "Immune infiltration analysis showed that Hmox1 was closely associated with NK cells in Alzheimer’s disease." (PMID 35923893, 2022). "Several lines of evidence highlighted the HMOX1 dysfunction related to brain inflammation and neurodegeneration, comprising Parkinson’s and Alzheimer’s diseases." (PMID 40636521, 2025). "The three top hits, HO-1 (heme oxygenase-1), MIOS, and SYNE2, exert diverse functions, yet each has been linked to neurodegeneration and Alzheimer’s disease." (PMID 37919601, 2024). "Recent findings highlight the neuroprotective effects associated with Nrf2-mediated induction of heme oxygenase-1 (HO-1) in diverse pathological conditions such as Alzheimer’s disease, Parkinson’s disease, and others." (PMID 38259497, 2023). "The neuroprotective effects of sulfuretin in Alzheimer’s disease are thought to occur through activation of nuclear factor erythroid 2-related factor 2 (Nrf2)-dependent heme oxygenase-1 (Ho-1) expression via the PI3K/Akt signaling pathway." (PMID 38145049, 2023). "Cyclophilin A (CypA), heme oxygenase-1 (HO-1), and inositol-requiring enzyme 1 (IRE1) are believed to be associated with Alzheimer’s disease (AD)." (PMID 33919311, 2021). "Moreover, an up-regulation of HMOX1 expression (resulting in increase of oxidative stress and sequestration of iron non-linked to transferrin in the mitochondrial department) has been found in the brains of patients with PD, Alzheimer's disease, and multiple sclerosis." (PMID 26313808, 2015). "Heme oxygenase-1 (HO-1), an inducible enzyme up-regulated in Alzheimer's disease, catabolises heme to biliverdin, Fe2+ and carbon monoxide (CO)." (PMID 25501830, 2014). "Interestingly, over-expression of HMOX1 in brain has been reported in Alzheimer’s disease (AD), PD, multiple sclerosis (MS), and other degenerative and nondegenerative CNS diseases." (PMID 30115913, 2018). "Moreover, an up-regulation of HMOX1 expression has been found in the brains of patients with PD, Alzheimer’s disease, and multiple sclerosis." (PMID 26868429, 2016). "In Alzheimer’s disease mice, cangrelor may reverse Aβ1−42-induced cognition deficits by inhibiting oxidative stress, neuroinflammation, and synaptic dysfunction mediated by nuclear factor E2-related factor 2 (Nrf2)/heme oxygenase 1 (HO-1) and NF-κB signaling." (PMID 39736771, 2024). "A previous study in a model of Alzheimer’s disease showed that Hmox1 expression might not always be related to Nrf2." (PMID 35216124, 2022).
Parkinson disease (97 papers, 2010 to 2026). A progressive degenerative disorder of the central nervous system characterized by loss of dopamine producing neurons in the substantia nigra and the presence of Lewy bodies in the substantia nigra and locus coeruleus. "HMOX1 genotype and allele frequencies in patients with Parkinson's disease according to phenotypes." (PMID 25309329, 2014). "In Parkinson’s disease, natural compounds such as thoninigianin A increase heme oxygenase-1 (HO-1) protein levels by activating a related pathway and modulating glutathione metabolism, thereby inhibiting ferroptosis." (PMID 40143112, 2025). "Such known miRNAs involved in α‐Syn regulation are named: miR‐153 and miR‐223 which they had experienced a downregulation in the brain, serum, and saliva of Parkinson's disease GFAP.HMOX1 transgenic mice model." (PMID 37434876, 2023). "Induction of the antioxidant enzyme heme oxygenase-1 (HO-1) was observed in both astrocytes and neurons in the substantia nigra of patients with Parkinson’s disease (PD)." (PMID 27097841, 2016). "Several reports suggested a role of heme oxygenase genes 1 and 2 (HMOX1 and HMOX2) in modifying the risk to develop Parkinson disease (PD)." (PMID 26091465, 2015). "Overexpression of Hmox1 contributes to mitochondrial damage in AD and Parkinson’s disease models." (PMID 31959236, 2020). "Increased oxidative stress and ROS can induce the expression of heme oxygenase-1 (HO-1) and increased HO-1 mRNA and protein expression have been reported in a wide spectrum of diseases including neurodegenerative diseases such as Parkinson disease." (PMID 31931835, 2020). "In addition, four genes associated with neurological disorders were significantly upregulated in hydrogel-cultured cells (NR4A2, Parkinson’s disease; A2M & HMOX1, Alzheimer’s; COL21A1, atypical psychosis)." (PMID 28097054, 2017). "The transcription factor Nrf2 (NF-E2-related factor 2) and its target gene products, including heme oxygenase-1 (HO-1), elicit an antioxidant response that may have therapeutic value for Parkinson's disease (PD)." (PMID 20676377, 2010). "Our study aimed at activating the NF-E2-related factor 2 (Nrf2)/heme oxygenase 1 (HO-1) redox system and increasing lipoxin A4 for the modulation of antioxidant stress and neuroinflammation through the action of two fungi in a rotenone-induced Parkinson’s model." (PMID 36289766, 2022). "Our findings indicate that miR-361-5p regulates the expression of HMOX1 and FADD, suggesting that miR-361-5p may represent a potential therapeutic target in Parkinson's disease." (PMID 41203125, 2025). "Previous studies have reported that selective overexpression of HO-1 in astrocytes in GFAP.HMOX1 transgenic mice from 8.5 to 19 months of age lead to the behavioral, neuropathologic, and molecular biological characteristics of parkinsonism." (PMID 33643023, 2021). "It has also been reported that BAI protects rat pheochromocytoma cells against 6-hydroxydopamine-induced neurotoxicity through the activation of Keap1/NRF2/HMOX1 pathway, indicating the potential use of BAI to prevent neurodegenerative diseases such as Parkinson’s disease." (PMID 32526964, 2020).
acute kidney injury (96 papers, 2008 to 2026). Sudden and sustained deterioration of the kidney function characterized by decreased glomerular filtration rate, increased serum creatinine or oliguria. "This supports the notion that Hmox1 fundamentally governs energy homeostasis in response to heme exposure, potentially underlying hemolysis-induced acute renal failure." (PMID 41550715, 2026). "Septic, critically ill patients carrying a short GTn allele in the HMOX1 promoter region have high plasma HMOX1 concentration and are associated with the development of acute kidney injury." (PMID 38509740, 2024). "Heme oxygenase-1 (HO-1), which is the rate-limiting enzyme in the catabolism of heme and the primary inducer of HO-1, is induced in the kidney in a rodent model of rhabdomyolysis-associated acute kidney injury (RM-AKI)." (PMID 28704479, 2017). "Odds ratios for HMOX1 risk alleles and acute kidney injury in different genetic risk models." (PMID 31120979, 2019). "In another study, TMZ alleviated folate-induced acute kidney injury in mice mainly by stimulating HIF-1α/heme oxygenase-1 (HO-1)." (PMID 39108756, 2024). "A study on rabbits with acute kidney injury revealed that EA treatment enhanced the expression of phosphorylated Akt, heme oxygenase-1 protein, Nrf2 total protein, and nuclear protein to resist oxidative stress." (PMID 37675019, 2022). "In this study, we showed, for the first time, that hyperbaric oxygen preconditioning upregulates heme oxygenase-1 and anti-apoptotic Bcl-2 protein expression in postischemic acute kidney injury induced in spontaneously hypertensive rats." (PMID 33573145, 2021). "Hong and Lu demonstrated that RvDs and PD1 repress renal interstitial fibrosis, and PD1 inhibits the inflammatory response and promotes renoprotective heme-oxygenase-1 expression during acute kidney injury." (PMID 26485038, 2015). "Intervention to increase the expression of heme oxygenase-1 in kidneys played a role in bilirubin protective effect in renal failure." (PMID 26251679, 2015). "Bilirubin levels may become elevated as a result of heme oxygenase-1 activation, occurring in exercise-induced acute kidney injury in patients with RHUC; this phenomenon suggests renal ischemia-reperfusion injury." (PMID 31771519, 2019). "Free heme, a pro-oxidant released from myoglobin, is thought to contribute to the pathogenesis of rhabdomyolysis-associated acute kidney injury (RM-AKI), because renal overexpression of heme oxygenase-1 (HO-1), the rate-limiting enzyme in heme catabolism, confers protection against RM-AKI." (PMID 28704479, 2017). "In a recently published study employing an ischemic acute kidney injury (AKI) mouse model, 6-shogaol (20 mg/kg, i.p.)exhibited protective effects against renal ischemia-reperfusion injury by interfering with the NFκB and heme oxygenase 1 (HO-1) signaling pathways." (PMID 34203813, 2021). "Through activation of the nuclear factor-erythroid 2-related factor-2- (Nrf2-) targeting antioxidant response element (ARE)/heme oxygenase-1 (HO-1) signaling cascade, DSS has attenuated acute kidney injury." (PMID 29670682, 2018).
Cerebral ischemia (94 papers, 2010 to 2025). Restriction of arterial blood supply to the brain associated with insufficient oxygenation to support the metabolic requirements of the tissue. "Nrf2 upregulates heme oxygenase-1 (HO-1), which protects against cerebral ischemia by maintaining nitric oxide bioavailability." (PMID 38902829, 2024). "Previous studies have shown that natural products or Chinese herbs exert a neuroprotective role against cerebral ischemia by activating the Nrf2/heme oxygenase 1 (HO-1) pathway." (PMID 37654609, 2023). "The upregulation of HMOX1 during cerebral ischemia revealed a protective effect on neuronal cell against oxidative stress." (PMID 33732102, 2021). "Heme oxygenase-1 (HO-1) is induced in astrocytes and exerts various important roles in angiogenesis and mitochondrial biogenesis in them following cerebral ischemia in mice." (PMID 34884886, 2021). "In resveratrol-treated rats, levels of nuclear factor erythroid 2-related factor (Nrf2) and heme oxygenase-1 (HO-1) were increased, indicating a reduction in oxidative damage during cerebral ischemia." (PMID 34681206, 2021). "Levels of nuclear factor erythroid 2-related factor (Nrf2) and heme oxygenase-1 (HO-1) were upregulated in the resveratrol-treated group, suggesting reduction in oxidative damage during cerebral ischemia." (PMID 29522491, 2018). "This study aimed to determine the effect of liraglutide pretreatment and to elucidate the mechanism of nuclear factor erythroid 2-related factor (Nrf2)/heme oxygenase-1 (HO-1) signaling after focal cerebral ischemia injury in diabetic rats model." (PMID 29623090, 2018). "Ligustrazine exhibits neuroprotective and anti-inflammatory effects on brain disorders such as cerebral ischemia, through elevating nuclear factor E2-related factor 2 (Nrf2)/heme oxygenase-1 (HO-1) expression." (PMID 26999089, 2016). "A Western blot analysis demonstrated the upregulation of nuclear factor erythroid 2–related factor 2 (Nrf2), heme oxygenase-1 (HO-1), and NAD(P)H:quinone oxidoreductase 1 (NQO1) and the downregulation of Kelch-like, ECH-associated protein 1 (Keap1) in the cerebral ischemia–reperfusion model." (PMID 40283984, 2025). "Previous studies have revealed that decreased expression of nuclear factor E2-related factor 2 (Nrf2) and heme oxygenase-1 (HO-1) contributes to aggravation of brain damage by increasing the infarct volume and decreasing neurological function, during cerebral ischemia." (PMID 35222793, 2022). "Some studies confirmed that heme oxygenase-1 (HO-1) and NAD(P)H quinone oxidoreductase 1 (NQO1) expression increased after cerebral ischemia." (PMID 36552584, 2022). "Additionally, cerebral ischemia was found to produce large amounts of ROS that activate NRF2 and stimulate the transcription of the antioxidant genes heme oxygenase-1 (HO-1), and others." (PMID 38834843, 2024). "Nrf2 activated by salidroside could bind to antioxidant response elements (AREs) such as heme oxygenase-1 (HO-1), SOD, and GSH-Px and could be upregulated to mediate neuroprotection and antioxidative stress in cerebral ischemia." (PMID 35462916, 2022).